HCAR1 (hydroxycarboxylic acid receptor 1)
Description:
Acts as a receptor for L-lactate and mediates its anti-lipolytic effect through a G(i)-protein-mediated pathway.
Synonyms: GPR104; GPR81; HCA1; FKSG80; TA-GPCR; LACR1; TAGPCR
Tractability: Small molecule: it belongs to a druggable protein family. Antibody: its Gene Ontology location is reachable by antibodies, with high confidence; UniProt places it where antibodies can reach, with medium confidence; UniProt predicts a signal peptide or a membrane-spanning region. PROTAC: a small molecule that binds it is known.
Target class: Family A G protein-coupled receptor; Small molecule receptor (family A GPCR); Carboxylic acid receptor; Hydroxycarboxylic acid receptor; Membrane receptor
Gene: Protein-coding gene on chromosome 12 (122,726,076 to 122,730,844, reverse strand). Ensembl gene ENSG00000196917.
Subcellular location: Cell membrane
Pathways (Reactome):
Signal Transduction: G alpha (i) signalling events; Hydroxycarboxylic acid-binding receptors
Gene Ontology:
Molecular function: G protein-coupled receptor activity; protein binding
Biological process: adenylate cyclase-inhibiting G protein-coupled receptor signaling pathway; negative regulation of lipid catabolic process; G protein-coupled receptor signaling pathway
Cellular component: plasma membrane; membrane
Genetic constraint (gnomAD): Loss-of-function variants: 0 observed, 0.8 expected, observed/expected ratio (o/e) 0, 90% interval 0 to 1.77. That is too few expected variants to judge how well the gene tolerates losing a copy. Missense variants: 445 observed, 470.81 expected, observed/expected ratio (o/e) 0.95, 90% interval 0.87 to 1.02. Synonymous variants: 183 observed, 190.42 expected, observed/expected ratio (o/e) 0.96, 90% interval 0.85 to 1.09.
Homologues: Orthologues: chimpanzee HCAR1 (99% identical), macaque HCAR1 (95% identical), pig HCAR1 (83% identical), dog HCAR1 (82% identical), mouse Hcar1 (80% identical), rat Hcar1 (79% identical), rabbit HCAR1 (77% identical), guinea pig HCAR1 (70% identical). Paralogues in human: HCAR2 (51% identical), HCAR3 (51% identical), OXER1 (33% identical), GPR31 (29% identical), P2RY2 (23% identical), P2RY1 (23% identical), P2RY4 (21% identical), P2RY6 (21% identical), SUCNR1 (20% identical), OXGR1 (20% identical), FFAR3 (19% identical), GPR42 (18% identical), and 3 more.
Diseases named in the same sentence as HCAR1 in open-access papers:
HCAR1 is named in the same sentence as 85 diseases in open-access papers, as found by Europe PMC text mining. Sharing a sentence is not in itself a finding about the gene and the disease. The quoted sentences say what the papers report.
breast carcinoma (34 papers, 2015 to 2025). "Furthermore, activation of HCAR1 by breast cancer cell-secreted lactate in tumor-associated dendritic cells has been shown to disrupt antigen presentation, thus aiding in immune evasion of cancer cells." (PMID 39766077, 2024). "While in dendritic cells of mice with breast cancer, HCAR1 activation is also shown to reduce the production of IL-6 and IL-12." (PMID 36615018, 2022). "Though better known for regulating lipid metabolism in adipocytes, more recently, HCARs have been functionally associated with breast cancer proliferation/survival; HCAR2 has been described as a tumor suppressor and HCAR1 and HCAR3 as oncogenes." (PMID 34852802, 2021). "Silencing of HCAR1 in breast cancer cells reduces their proliferation rate and promote their apoptosis." (PMID 33113952, 2020). "Recently, the presence of HCAR1 has been shown to be crucial for pancreatic and breast cancer cell survival." (PMID 26208712, 2015). "We report that TME lactate triggers the assembly of the lactate receptor hydroxycarboxylic acid receptor 1 (HCAR1)-associated protein complex, which includes GRB2, SOS1, KRAS, GAB1, and PI3K, for the activation of both the RAS and the PI3K oncogenic signaling pathways in breast cancer (BCa) cells." (PMID 39199589, 2024). "Moreover, there has been evidence that HCAR1 may also play a role in restricting the growth of tamoxifen-resistant breast cancer cells by altering fatty acid metabolism." (PMID 39766077, 2024). "Thus, we sought to identify germline variants in HCAR1, HCAR2, and HCAR3 that could potentially be associated with breast cancer risk." (PMID 34852802, 2021). "Lactate stimulates the expression of its own receptor and, maybe, because of that, high expression of HCAR1 has been detected in pancreatic tumors, in breast cancer and in cell lines from colon, breast, lung, hepatocellular, salivary gland, cervical, and pancreatic carcinomas." (PMID 33113952, 2020). "In the context of breast cancer, lactate within the TME triggers the assembly of the hydroxycarboxylic acid receptor 1 (HCAR1), thereby activating downstream RAS and PI3K oncogenic signaling pathways, which are instrumental in promoting cancer progression." (PMID 40165895, 2025).
pancreatic cancer (20 papers, 2016 to 2026). "Consistently, a study performed in HCAR1-silenced pancreatic cancer cells led to reduced mitochondrial activity and survival in several cancer cell." (PMID 35574309, 2022). "Silencing HCAR1 in cancer cells also inhibits the growth of breast and pancreatic tumors in vivo, and in the last case, a reduced metastatic potential has been observed." (PMID 33113952, 2020). "Additionally, HCAR1 expression levels correlated with pancreatic tumor growth and metastasis in animals and was shown to be required for lactate stimulated MCT expression in pancreatic cancer cells." (PMID 40333742, 2025).
colitis (15 papers, 2020 to 2025). Inflammation of the colon. "D-lactate exhibits anti-inflammatory effects in experimental models of colitis and endotoxemia, through a specific receptor known as GPR81 (formerly hydroxycarboxylic acid receptor 1, HCAR1)." (PMID 39744722, 2024).
cervical carcinoma (9 papers, 2015 to 2025). A carcinoma arising from either the exocervical squamous epithelium or the endocervical glandular epithelium. "Hydroxycarboxylic acid receptor 1 (HCAR1) was previously reported to be involved in the enhancement of DNA repair in cervical cancer cells related to lactic acid." (PMID 36468004, 2022). "The expression of lactic acid receptor/HCAR1 helps to regulate the mechanism of DNA repair in cervical cancer cells." (PMID 36468004, 2022). "For example, the lactate receptor (HCAR1/GPR81) has been reported to be responsible for ABCB1 up-regulation in human cervical cancer cells to mediate doxorubicin resistance." (PMID 33593355, 2021). "In the present study, we demonstrated that cervical cancer cell lines display HCAR1 surface expression and that both lactate isomers induced signalling pathways in a receptor-dependent fashion." (PMID 26208712, 2015). "To evaluate the potential role of HCAR1 in the response of cervical cancer cells to chemotherapeutics, we first assessed the expression of this receptor in three cervical cell lines: HeLa, Ca Ski and C33A." (PMID 26208712, 2015). "Furthermore, we demonstrated the essential role of HCAR1 and MCTs in the lactate-mediated enhancement of cellular DNA repair capacity and in the resistance of the examined cervical cancer cell lines to anticancer chemotherapeutics." (PMID 26208712, 2015). "Interestingly, the enhancement of cervical cancer cell survival by L-lactate treatment corresponded to the HCAR1 protein level in the respective cell lines." (PMID 26208712, 2015). "In addition, we showed that all three examined cervical cancer cell lines display surface expression of HCAR1, which is known to be involved in cell survival." (PMID 26208712, 2015). "Thus, targeting lactate-mediated signalling in cervical cancer environment, e.g. by locally delivered MCTs inhibitors and/or HCAR1 antagonist, might improve efficacy of anticancer therapy." (PMID 26208712, 2015). "To further explore the mechanism by which HCAR1 is involved in the lactate-mediated enhancement of DNA repair and cervical carcinoma cell survival, we studied the kinetics of γ-H2AX foci formation in cells expressing reduced level of HCAR1." (PMID 26208712, 2015).
hepatocellular carcinoma (9 papers, 2021 to 2025). A malignant tumor that arises from hepatocytes. "Hepatocellular carcinoma cells (HCCs) efficiently uptake lactic acid through transporters like hydroxycarboxylic acid receptor 1 (HCAR1) and monocarboxylate transporter 1 (MCT1)." (PMID 38217037, 2024). "Importantly, glycolysis inhibition and reduced extracellular lactate levels were accompanied by the downregulation of lactate hydroxycarboxylic acid receptor-1 (HCAR-1/GPR81) in hepatic carcinoma cells." (PMID 34201298, 2021). "High levels of lactic acid upregulate the expression of hydroxycarboxylic acid receptor 1 (HCAR1) and monocarboxylate transporter 1 (MCT1), thereby reducing lipid peroxidation and inhibiting ferroptosis in hepatoma cells." (PMID 39273090, 2024). "Inhibition of hydroxycarboxylic acid receptor 1 (HCAR1) or monocarboxylate transporter 1 (MCT1) blocks lactate uptake and reduces ATP production in hepatocellular carcinoma cells, resulting in the activation of AMPK signaling and ferroptosis." (PMID 37860928, 2023). "Lactic acid can induce the formation of monounsaturated fatty acids through the HCAR1/MCT1-SREBP1-SCD1 pathway and resist oxidative stress-induced ferroptosis in hepatocellular carcinoma (HCC) cells." (PMID 35795552, 2022).
breast tumor (6 papers, 2016 to 2025). "In a HCAR1-deficient breast tumor animal model, a paracrine regulation of cancer cell-secreted lactate on dendritic cell (DC) surface HCAR1 activation and subsequent suppression of DC presentation of tumor-specific antigen to other immune cells was observed." (PMID 40333742, 2025).
Anxiety (5 papers, 2023 to 2025). Intense feelings of nervousness, tension, or panic often arise in response to interpersonal stresses. "We next evaluated the anxiety level of HCAR1 deficient animals, as a strongly associated co-morbid symptom of ASD, by performing elevated plus maze test." (PMID 37940970, 2023). "Overall, these features of HCAR1-deficient animals display anxiety-like behavior, pointing to a significant role for HCAR1 in regulating genes implicated in behavior which otherwise leads to autistic-like behaviors." (PMID 37940970, 2023). "While lactate treatment doesn’t seem to affect anxiety via HCAR1, the behavioral effects of HCAR1 activation after stroke remain to be elucidated." (PMID 41160759, 2025). "Interestingly, a recent study reported that HCAR1 KO mice exhibit differences in certain social, anxiety, and, repetitive behaviors in an autism-like manner." (PMID 40345852, 2025).
glaucoma (5 papers, 2018 to 2025). Increased pressure in the eyeball due to obstruction of the outflow of aqueous humor. "The increased expression of hydroxycarboxylic acid receptor 1 (HCAR1) is associated with anti-inflammatory response in glaucoma." (PMID 35203642, 2022). "Therefore, our data suggests that the ketogenic diet exerts its anti-inflammatory response in glaucoma not only through the inhibition of AMPK-NF-κB signaling but also via induction of HCAR1-mediated inhibition of NLRP3 inflammasome." (PMID 30424795, 2018). "We detected significantly increased mRNA and protein levels of HCAR1 but not HCAR2 in D2 retina and ON, indicating that ketogenic diet treatment induces HCAR1 expression in glaucoma mice." (PMID 30424795, 2018).
glioblastoma (5 papers, 2022 to 2025). The most malignant astrocytic tumor (WHO grade IV). "However, diverting from our observations, HCAR1 activation has been reported to augment the proliferation, survival, and metastasis of various cancer cell lines, including colorectal, breast, ovarian, pancreatic, hepatocellular, and glioblastoma, thus marking this MMR as an oncogene." (PMID 39766077, 2024).
idiopathic pulmonary fibrosis (5 papers, 2023 to 2024). Idiopathic pulmonary fibrosis (IPF) is a nonneoplastic pulmonary disease that is characterized by the formation of scar tissue within the lungs in the absence of any known cause. "We found an increased lipid droplets in A549 cells following lactate stimulation, and the activation of lactate-HCAR1 signaling aggravated BLM-induced lung fibrosis in vivo, while significantly enhancing the accumulation of lipids in lungs." (PMID 38760881, 2024). "As shown, the expression of pulmonary fibrosis markers was significantly upregulated after BLM treatment, and the activation of HCAR1 exacerbated this change, suggesting that the activation of lactate signaling exacerbates the progression of pulmonary fibrosis in vivo." (PMID 38760881, 2024).
Stroke (5 papers, 2021 to 2025). Sudden impairment of blood flow to a part of the brain due to occlusion or rupture of an artery to the brain. "The discovery of HCAR1, present in the brain, prompted the idea of a possible dual-protective effect of lactate in the context of stroke; a metabolic effect and a signaling effect mediated (possibly) by HCAR1." (PMID 35629969, 2022). "Furthermore, we and others have shown that HCAR1 promotes neurogenesis and microglia activation and we have demonstrated that only two lactate injections 24 and 48 hours after stroke lead to almost 50% reduced lesion size via HCAR1 activation." (PMID 41160759, 2025). "Additionally, in light of these results, we would disregard HCAR1 activation as an interesting therapeutic strategy for stroke patients." (PMID 35629969, 2022). "The overstimulation of the neuronal HCAR1 in the acute post-stroke phase could therefore, lead to a detrimental exacerbation of neuronal activity, instead of slowing it down to balance the effects caused by the excessive extracellular glutamate that accumulates after hypoxia-ischemia." (PMID 34093243, 2021). "The lack of HCAR1 could, therefore, alter the role played by these and maybe other lactate-sensitive pathways, which could turn out to be beneficial for recovery from stroke." (PMID 35629969, 2022).
Hypertension (4 papers, 2021 to 2025). The presence of chronic increased pressure in the systemic arterial system. "Novel HCAR1 agonists can also induce hypertension in several species." (PMID 33802976, 2021).
ischemia (4 papers, 2021 to 2025). A hypoperfusion of the BLOOD through an organ or tissue caused by a PATHOLOGIC CONSTRICTION or obstruction of its BLOOD VESSELS, or an absence of BLOOD CIRCULATION. "In injury situations, such as ischemia, high levels of glutamate contribute to an increase in lactate released by astrocytes, which, through HCAR1, attenuate cAMP levels and Ca2+ influx, promoting neuroprotection in astrocytes." (PMID 38276297, 2023). "Based on the data from in vitro experiments, one would expect a protective effect following administration of the lactate receptor agonists, as the extracellular activation of neuronal HCAR1 would slow down neuronal activity, exacerbated after the ischemia." (PMID 34093243, 2021).
glioma (3 papers, 2022 to 2023). A benign or malignant brain and spinal cord tumor that arises from glial cells (astrocytes, oligodendrocytes, ependymal cells). "Considering the discrepant behavior between astrocytes and C6 glioma cells in some aspects, we investigated the distribution of HCAR1 expression and content in C6 cells." (PMID 38276297, 2023). "One is that lactate signaling via HCAR1 for S100B secretion is less important in C6 glioma cells." (PMID 38276297, 2023). "Furthermore, the immunocytochemical image of HCAR1 points to the presence in the plasma and perinuclear membrane of this receptor in C6 glioma cells." (PMID 38276297, 2023). "However, we can see via immunofluorescence that C6 glioma cells express HCAR1, and we compared this cell type with a primary astrocyte culture via Western blotting, finding that C6 glioma cells have more HCAR1 content than primary astrocyte cultures (p = 0.0168)." (PMID 38276297, 2023).
Obesity (3 papers, 2020 to 2021). Accumulation of substantial excess body fat. "As obesity is strongly associated with increased lipolysis in adipocytes, reduced HCAR1 expression and as a result, increased lipolysis in male DIO mice can cause hyperglycemia." (PMID 31999787, 2020). "As basal lipolysis in adipocytes was elevated during obesity and was closely associated with insulin resistance, inhibition of lipolysis through activation of HCAR1 in adipose tissue BAT would be an alternative way to control glycemia in individual with type 2 diabetes." (PMID 31999787, 2020). "The most upregulated gene was Hydroxycarboxylic acid receptor 1 (HCAR1), which is activated by lactic acid and blockade of HCAR1 may prevent and treat obesity." (PMID 33802976, 2021).
ovarian carcinoma (3 papers, 2022 to 2025). A malignant neoplasm originating from the surface ovarian epithelium. "Unsurprisingly, HCAR1 protein expression was observed across all histological subtypes of ovarian cancer, with localisation primarily around cellular membranes, in accordance with GPCR distribution." (PMID 36615018, 2022). "Recent studies have identified lactate as a ligand for GPR68, GPR81, and GPR132, also known as ovarian cancer G protein-coupled receptor 1 (OGR1), hydroxy-carboxylic acid receptor 1 (HCAR1) and G2 accumulation protein (G2A), respectively." (PMID 40046050, 2025). "Shi et al21 found that NL01, the derivative of curcumin, not only induced ferroptosis in ovarian cancer cells through reducing HCAR1/MCT1 expression and activating the AMPK/SREBP1 pathway in vitro but also promoted iron death and repressed ovarian cancer growth in xenograft mouse models." (PMID 39150386, 2024).
Alzheimer disease (2 papers, 2020 to 2023). A progressive, neurodegenerative disease characterized by loss of function and death of nerve cells in several areas of the brain leading to loss of cognitive function such as memory and language. "In addition, lactate has been shown to protect against inflammation through an HCAR1-mediated mechanism, which may be an important component of the pathology of Alzheimer’s disease." (PMID 31934509, 2020).
autism (2 papers, 2023 to 2025). Persistent deficits in social interaction and communication and interaction as well as a markedly restricted repertoire of activity and interest as well as repetitive patterns of behavior. "Accordingly, modulation of HCAR1 could potentially serve as a therapeutic target for autism, opening new avenues for investigation in this context." (PMID 37940970, 2023). "It would be tempting to speculate that lack or disruption of HCAR1 signaling could participate in hyperactive neural firings that contribute to manifestations of autism." (PMID 37940970, 2023).
brain injuries (2 papers, 2021 to 2022). "Hence, to further ascertain whether the stimulation of HCAR1 could be considered as an interesting therapeutic option aimed at neuroprotection in acute brain injuries, we tested the effects of its absence in mice subjected to transient MCAO." (PMID 35629969, 2022).
diabetes (2 papers, 2021 to 2024). "Similar to our results, some studies have shown that lactate inhibits the HCAR1/PKA/CREB pathway in the brain of diabetes-associated cognitive decline rats." (PMID 34720870, 2021).